MGMT (O-6-methylguanine-DNA methyltransferase)
Diseases named in the same sentence as MGMT in open-access papers (continued):
Sharing a sentence is not in itself a finding about the gene and the disease.
bladder cancer (7 papers, 2014 to 2025). "A recent study also suggested that a high MGMT expression level can be a poor prognostic factor in patients with bladder cancer receiving platinum-based drugs as an adjuvant therapy." (PMID 31450627, 2019). "The RNA expression of RASSF1A, APC and MGMT was also found to be decreased in the muscle-invasive high grade bladder cancer when compared to the non muscle invasive low grade group (p-value < 0.05)." (PMID 24790823, 2014). "The promoter methylation at MGMT has been reported in many human cancers but found to be less frequent in bladder cancer." (PMID 24790823, 2014). "Our study shows a prominent MGMT hypermethylation in the invasive high grade bladder cancer as well as the non-invasive low grade cancer and the findings were correlated in the plasma samples." (PMID 24790823, 2014). "However, only APC and MGMT showed significance (p < 0.001) in the muscle invasive high grade bladder cancer when it was compared with the normal bladder mucosa." (PMID 24790823, 2014). "Interestingly, the findings from formalin fixed paraffin embedded samples were comparable to the plasma samples of invasive high grade bladder cancer patients for CDKN2A, MGMT and RASSF1A." (PMID 24790823, 2014).
breast tumors (7 papers, 2005 to 2021). "There are numerous other studies dealing with MGMT promoter methylation, MGMT mRNA expression and MGMT protein expression or MGMT protein activity in breast tumors and other diseases." (PMID 32841306, 2020). "Conversely, a recent study demonstrated the predictive value of MGMT protein expression in breast tumor biopsies obtained prior to CPM-containing neoadjuvant chemotherapy." (PMID 24932232, 2014). "Several groups have measured MGMT expression in human breast tumours and report activity that is low, moderate or high." (PMID 16278661, 2005). "We have previously reported almost uniformly high levels of MGMT in breast tumours as determined by functional assay and immunohistochemical analysis." (PMID 16278661, 2005). "In order to establish if this resistance can be reversed in model systems, we have used the human breast adenocarcinoma cell line, MCF-7, that, like many of the breast tumours we have examined, expresses very high levels of MGMT." (PMID 16278661, 2005). "In breast tumors, MGMT expression can be up to 4-fold higher compared with normal breast tissues." (PMID 24932232, 2014). "For example, a low rate of promoter methylation was observed for the TUSC3 (9/105 samples), MGMT (8/105 samples) and CDKN2B (2/105 samples) genes in breast tumors." (PMID 23472065, 2013). "The methylation of three of them (ESR1, MGMT and WT1) has been widely reported in breast tumors." (PMID 22011321, 2011).
lymphopenia (7 papers, 2012 to 2025). Reduction in the number of lymphocytes. "The development of lymphopenia by temozolomide can be caused by the negligible expression of MGMT and/or multidrug resistance proteins in peripheral blood lymphocytes." (PMID 38390330, 2024). "Reduced expression of DNA-repair enzyme O-6-methylguanine-DNA-methyltransferase (MGMT) in mature monocytes and further deletion of MGMT by TMZ have been determined to be the cause of lymphopenia." (PMID 25247196, 2014). "Deletion of O6-methylguanine-DNA-methyltransferase (MGMT) activity, a DNA repair enzyme, by temozolomide has been determined to be the cause of lymphopenia." (PMID 23133490, 2012). "RT-induced lymphopenia restricts synergy with immunotherapy, but MGMT methylation identifies patients with favorable immune microenvironments, and PT may reduce lymphopenia to enhance combined therapies." (PMID 41007699, 2025). "For trial enrollment, particular consideration should be given to patients without grade 2-4 lymphopenia, who are not expected to require steroids, and with an unmethylated MGMT promoter, for whom lymphotoxic temozolomide have to be completely omitted." (PMID 38390330, 2024).
oligodendroglial tumor (7 papers, 2009 to 2022). Oligodendrogliomas are cerebral tumors that are differentiated from other gliomas on the basis of their unique genetic characteristics and better response to chemotherapy. "We demonstrated that higher methylation levels of LINE-1 and the MGMT promoter and 1p/19q codeletion were associated with oligodendroglial tumors." (PMID 21829728, 2011). "In WHO grade III oligodendroglial tumors, the hypermethylated phenotype has been recently described by the EORTC study 26951 as a better predictor of survival in comparison with MGMT methylation." (PMID 24083241, 2013). "There is also evidence that MGMT hypermethylation and low or absent expression are frequent in oligodendroglial tumors and likely contribute to the chemosensitivity and improved outcomes of these tumors." (PMID 22553975, 2012).
oral squamous cell carcinoma (7 papers, 2014 to 2024). "Loss of MGMT expression in patients with oral squamous cell carcinoma is associated with advanced stage, lymph node positivity, and poor prognosis." (PMID 33976347, 2021). "A study of patients with oral squamous cell carcinoma reported by Sawhney and colleagues found a gradual loss of expression of MGMT during the transition from hyperplasia to dysplasia, suggesting that a diminution in MGMT expression might be a critical step in oral tumorigenesis." (PMID 33033516, 2020). "Silencing TET1 increases cisplatin sensitivity by altering the expression of multiple genes in various pathological conditions including vimentin in OVCA, and o6-methylguanine-DNA methyltransferase (MGMT) in oral squamous cell carcinoma (OSCC)." (PMID 38216951, 2024). "The aims of this study were to evaluate MHL1 and MGMT methylation levels in oral squamous cell carcinoma (OSCC) and oral potentially malignant disorders (OPMDs), and to integrate this information with The Cancer Genome Atlas (TCGA) database." (PMID 35888599, 2022). "Promoter methylation and relative gene expression of O6-methyguanine-DNA-methyltransferase (MGMT) and p16 genes were examined in tissue and blood samples of patients with premalignant oral lesions (PMOLs) and oral squamous cell carcinoma (OSCC)." (PMID 24991542, 2014).
thyroid cancer (7 papers, 2013 to 2025). "Further investigation is needed to decipher the functional properties of the methyltransferase encoded by MGMT and to understand how alteration of such functions may lead to the development of the most common type of thyroid cancer." (PMID 28499365, 2017). "Moreover MGMT methylation is reported in a group of discriminating methylation markers that differentiate thyroid cancer from benign nodules." (PMID 31754358, 2019). "Moreover, MGMT methylation was reported in MLH1 and MGMT expression and their consequence in genomic instability in patients with thyroid carcinoma." (PMID 31754358, 2019). "Nevertheless, a link between MGMT and thyroid cancer had already been established in few studies." (PMID 28499365, 2017). "Using this approach, two genes, namely ERCC5 and MGMT were significantly associated (PGene < 0.05) with PTC susceptibility, suggesting that DR, BER, and NER DNA repair mechanisms may all play a role in the development of thyroid cancer." (PMID 28499365, 2017).
dysplasia (6 papers, 2008 to 2025). A usually neoplastic transformation of the cell, associated with altered architectural tissue patterns. "It has been shown that serrated adenomas with dysplasia are more associated with MGMT methylation compared to hyperplastic polyps and serrated adenomas without dysplasia." (PMID 24151575, 2013). "We found significant MGMT methylation in blood samples of leukoplakia with and without dysplasia and OSCC groups as compared to controls." (PMID 24991542, 2014). "The mRNA expression of MGMT and p16 genes was significantly downregulated in both tissue and blood samples of premalignant oral lesions (leukoplakia with and without dysplasia, and SMF) and OSCC (P ≤ 0.05)." (PMID 24991542, 2014). "Among premalignant oral lesions, MGMT methylation frequency in tissue samples was the highest for leukoplakia with dysplasia (73%, P = 0.0002) followed by leukoplakia without dysplasia (73%, P = 0.0015), SMF (46%, P = 0.0437), and OLP (25%, P = 0.4386 NS)." (PMID 24991542, 2014). "MGMT and p16 gene showed similar methylation pattern in tissue and blood DNA samples from patients with premalignant oral lesions (leukoplakia with and without dysplasia, SMF, and OLP) and OSCC." (PMID 24991542, 2014). "A recent study reported MGMT methylation in 46.7% of microvesicular hyperplastic polyps (MVHP), 60% of SSA/SSP without dysplasia, and 75% of SSA/SSP with dysplasia." (PMID 24151575, 2013).
epilepsy (6 papers, 2021 to 2024). A brain disorder characterized by episodes of abnormally increased neuronal discharge resulting in transient episodes of sensory or motor neurological dysfunction, or psychic dysfunction. "Noteworthy, the two KDM5C subgroups showed significant changes in NANOG expression in the subset of patients without epilepsy or with the wild-type IDH1/2 genotype or with MGMT methylation, while significant OCT4 change was found in the subset of patients with the wild-type IDH1/2 genotype." (PMID 36142158, 2022).
meningioma (6 papers, 2012 to 2023). A generally slow growing tumor attached to the dura mater. "VEGF, EGFR, EGFRvIII, PD-L1; and Sox2 expression; MGMT methylation status; and TERT promoter mutation were assessed in paired meningioma samples collected from the same patient before and after progression using immunohistochemistry and PCR." (PMID 36836440, 2023). "For this purpose, 44 WHO grade I meningiomas, including 8 showing regrowth after radiosurgery, were analysed for Ki-67 and NDRG4 protein expression, loss of 1p36 and promotor hypermethylation of the genes NDRG1-4, SFRP1, HOXA9 and MGMT." (PMID 34385566, 2021). "However, some of them, such as MGMT, need more research in order to prove their function on meningiomas." (PMID 33014773, 2020). "Recently, several studies have reported hypermethylation of MGMT in meningiomas." (PMID 33014773, 2020). "MSP for NDRG1-4, SFRP1, HOXA9 and MGMT was performed on 41 meningioma samples and 10 nontumoral control brain tissue samples." (PMID 34385566, 2021). "Although hypermethylation of MGMT did not correlate with regrowth, 35% of meningioma grade I patients showed hypermethylation of MGMT, which is relatively high in comparison with 0–22% in earlier reports." (PMID 34385566, 2021).
pituitary carcinomas (6 papers, 2014 to 2022). A primary or metastatic malignant neoplasm affecting the pituitary gland. "Low MGMT expression is more common in aggressive PitNETs and pituitary carcinomas than in non-aggressive PitNETs, and prolactinomas are more likely to have low MGMT expression than other subtypes." (PMID 35892862, 2022).
triple-negative breast carcinoma (6 papers, 2018 to 2024). An invasive breast carcinoma which is negative for expression of estrogen receptor (ER), progesterone receptor (PR), and human epidermal growth factor receptor 2 (HER2). "In ER negative breast cancer, the MGMT promoter is frequently methylated in a BRCA1 dependent manner, with highest rate of MGMT promoter methylation (>60%) in wild-type BRCA1 triple negative breast cancer." (PMID 30038716, 2018).
anaplastic oligodendroglioma (5 papers, 2019 to 2024). A WHO grade III oligodendroglioma with focal or diffuse malignant morphologic features (prominent nuclear pleomorphism, mitoses, and increased cellularity). "The EORTC26951 clinical trial retrospectively analyzed the methylation status of MGMT promoter in anaplastic oligodendroglioma patients." (PMID 32010632, 2019). "It was found that methylation of MGMT promoter in anaplastic oligodendroglioma patients predicted better overall survival (OS) and PFS, whether in radiotherapy alone or in sequential radiotherapy and chemotherapy group [chemotherapy regimen: procarbacine, lomustine (CCNU), vincristine (PCV)]." (PMID 32010632, 2019). "Elsewhere, it has been reported that methylation of MGMT promoter has no predictive value for chemosensitivity of anaplastic oligodendroglioma patients undergoing adjuvant PCV chemotherapy." (PMID 32010632, 2019).
corticotroph adenomas (5 papers, 2015 to 2025). "Reports of long-term remission describe a low expression of O-6-methylguanine-DNA methyltransferase (MGMT) a DNA repair enzyme commonly found in invasive corticotroph adenomas including CCA which has been noted to predict TMZ responsiveness." (PMID 40636382, 2025). "It has been suggested that type I silent corticotroph adenomas have lower levels of MGMT than clinically active ACTH-secreting tumors, then, they could be good candidates for TMZ treatment." (PMID 35928898, 2022). "However, in two recent reports, low-level MGMT expression (<25 %) was observed in 91.6 % of GH adenomas (n = 36), and 60 % of pituitary corticotroph adenomas (n = 40)." (PMID 26400193, 2015).
diffuse midline glioma (5 papers, 2018 to 2025). A diffuse glioma that arises from the midline structures of the central nervous system. "The following patients were excluded from analysis: 57 patients with unknown MGMT status, 26 patients with IDH-mutant GBM, 12 patients with leptomeningeal disease or gliomatosis, 3 infratentorial GBM, and 1 K27M-mutant diffuse midline glioma." (PMID 33235995, 2020).
esophageal adenocarcinoma (5 papers, 2008 to 2025). A malignant tumor with glandular differentiation arising predominantly from Barrett mucosa in the lower third of the esophagus. "Although up to 130 genes are associated with DNA repair, MGMT is the major gene in the pathway of DNA repair and has been frequently found to be silenced by CpG island hypermethylation in many cancers, including esophageal adenocarcinoma." (PMID 28353639, 2017).
esophageal squamous cell carcinoma (5 papers, 2010 to 2020). Esophageal squamous cell carcinoma (ESCC) is a type of esophageal carcinoma (EC) that can affect any part of the esophagus, but is usually located in the upper or middle third. "Polymorphic variation in the DNA repair capacity genes XPD and MGMT as well as ALD2 have been associated with increased esophageal SCC susceptibility in a Chinese population study." (PMID 24281163, 2010). "O6-methylguanine-DNA methyltransferase (MGMT) is mutated in 17.5% and methylated in 44% of human esophageal squamous cell carcinoma." (PMID 26967246, 2016).
Fanconi anemia (5 papers, 2011 to 2025). Fanconi anemia (FA) is a hereditary DNA repair disorder characterized by progressive pancytopenia with bone marrow failure, variable congenital malformations and predisposition to develop hematological or solid tumors. "TMZ lethality is driven by replication-dependent O6-methylguanine/mismatch-repair signaling, whereas BCNU kills through interstrand cross-links resolved by MGMT and Fanconi anemia/homologous recombination (FA/HR) pathways." (PMID 41271669, 2025). "Curcumin also inhibits DNA repair pathways in cancer cells, like the fanconi anemia/BRCA (FA/BRCA) pathway, or downregulates DNA repair proteins MGMT (O6-methylguanine-DNA methyltransferase), DNAPK, Ku70, Ku80, and ERCC-1." (PMID 22247744, 2011). "We therefore conclude that inhibition of the Fanconi Anaemia pathway offers promise as a chemo-sensitising strategy irrespective of MGMT status, which is an important finding for the future clinical development of FAPi." (PMID 25071006, 2014).
gastric tumor (5 papers, 2016 to 2020). "In a separate analysis, there was a significant association of MGMT promoter hypermethylation with lymph node (LN) metastasis of gastric tumor (OR = 1.56, CI = 1.14–2.13, P < .05), especially in Asians (OR = 1.64, CI = 1.18–2.29, P < .05)." (PMID 28445279, 2017). "MLH1 promoter methylation is more often detected in the early stages and in less aggressive gastric tumors, whereas MGMT promoter methylation is more typical of late-stage stomach adenocarcinomas and poor prognoses." (PMID 26810771, 2016). "In addition, MGMT promoter hypermethylation significantly promoted distant metastasis and lymph node (LN) metastasis of gastric tumor (for distant metastasis, OR = 4.22, CI = 2.42–7.37, P < .05; for LN metastasis, OR = 1.56, CI = 1.14–2.13, P < .05)." (PMID 28445279, 2017). "Furthermore, MGMT gene-promoter hypermethylation might promote the distant metastasis and LN metastasis of gastric tumor." (PMID 28445279, 2017). "Therefore, the MGMT promoter hypermethylation might encourage the metastasis of gastric tumor in Asians and decrease the survival rate of GC." (PMID 28445279, 2017).
Obesity (5 papers, 2014 to 2024). Accumulation of substantial excess body fat. "Given the important increase in oxidative DNA damage in obesity, upregulation of MGMT may be involved in the repair of DNA damages caused by obesity." (PMID 31921306, 2019). "Of note, obesity was associated with shorter survival in MGMT methylated, but not in MGMT unmethylated tumors." (PMID 35704157, 2022). "The finding of a negative effect of obesity on OS, at least in MGMT-methylated patients, is in line with a previous publication showing an association of obesity with reduced OS in a large retrospective case–control study, but inconsistent with results from a recent meta-analysis." (PMID 35704157, 2022).
seminoma (5 papers, 2017 to 2024). A radiosensitive malignant germ cell tumor found in the testis (especially undescended), and extragonadal sites (anterior mediastinum and pineal gland). "Similarly, a significant association of MGMT methylation frequency with the histological classification of the tumors was observed, in which 90.9% (20/22) of methylated cases were classified as non-seminomas (p=0.019)." (PMID 28881587, 2017). "We observed a high frequency of MGMT and CALCA methylation in NSGCTs and demonstrated for the first time that CALCA methylation is associated with non-seminoma tumors, refractory disease, and poor clinical outcome in TGCT patients (range, 26–32 years)." (PMID 34068019, 2021). "Seminomas are known to show selective hypermethylation at several tumor suppressors, such as MGMT, SCGB3A1, RASSF1A, HIC1, and PRSS21." (PMID 32176716, 2020). "The DPPA3 and XIST genes were hypermethylated in LT-PTCs as compared to d0-PTCs and seminomas, MGMT displayed a variable DNA methylation pattern between and within groups and the KIT promoter was stably hypomethylated in all groups including seminomas." (PMID 32176716, 2020). "Intriguingly, MGMT and RASSF1A methylation was investigated in a cohort of 41 patients from India, of whom 24 were seminoma patients, 4 were non-seminoma patients, and 13 had mixed tumors." (PMID 38791003, 2024). "In the case of MGMT, the results contradicted previous mentions, with none of the non-seminoma patients displaying methylation." (PMID 38791003, 2024). "Promoter hypermethylation of the RASSF1A and HIC1 genes was observed in resistant non-seminomas, while sensitive non-seminomas showed hypermethylation of MGMT and RARB." (PMID 35625709, 2022).